TNF (tumor necrosis factor)
Diseases named in the same sentence as TNF in open-access papers (continued):
Sharing a sentence is not in itself a finding about the gene and the disease.
ischemia (continued). "In particular, elevated fetal/neonatal levels of pro-inflammatory cytokines and chemokines—especially the tumor necrosis factor—can lead to fetal or neonatal brain injury, resulting in ischemia, intraventricular hemorrhage (IVH), and periventricular leukomalacia." (PMID 40724751, 2025). "Studies have shown that low levels of TNF-α may have a protective effect on the heart by enhancing myocardial tolerance to ischemia, and TNF-α may inhibit the expression of inflammatory cytokines such as IL-1, IL-2, and IL-6 in the heart." (PMID 40284832, 2025). "Similarly, in North India, TNFα and IL-6 levels were found to be higher in patients with ischemia-related CHF compared to patients with valvular and hypertensive heart failure." (PMID 38256155, 2024). "Furthermore, pathway analysis indicated that a combination of P2Y1R-ANT and MCM suppressed inflammatory pathways, including the MAPK/NF-κB/TNF-α or IL-1β signaling in reactive astrocytes after ischemia." (PMID 37676390, 2024). "In addition, the TM extract and its bioactive ingredients exert anti-inflammatory effects by downregulating a variety of proinflammatory mediators, such as TNF-α, IL-1β, and nitric oxide, in various models of ischemia-induced injury." (PMID 39391701, 2024). "The expression levels of inflammatory factors IL‐1β, TNF‐α, and IL‐6 were simultaneously increased in both the ipsilateral L Core and L Edge at 3 days post‐ischemia, whereas the levels of these factors in the L Cortex region were similar to the contralateral side." (PMID 39252446, 2024). "This experimental study demonstrated that pretreatment with the BRD4 selective inhibitor JQ1 prior to the induction of ischemia might dramatically reduce the level of inflammatory cytokines (TNF) compared to those in the control and vehicle groups." (PMID 37520478, 2023). "In addition, intravenous administration of hUC-MSCs effectively downregulated the expression of pro-inflammatory cytokines, including IL-1β, TNF-α, matrix metalloproteinase 9, and IL-6, which are upregulated by ischemia." (PMID 36829224, 2023). "Furthermore, in a model of renal ischemia, it has been observed that the TNF-α gene expression is highly elevated in injured kidney tissues following a nephrectomy of the right kidney and subsequent ischemia in the left kidney." (PMID 37675177, 2023). "TMZ reduces the release of proinflammatory mediators from macrophages induced by reactive oxygen species, including C-reactive protein (CRP), tumor necrosis factor-alpha (TNF-α), interleukin 1 (IL-1), and interleukin 8 (IL-8) during both inflammation and ischemia." (PMID 35538296, 2023). "It has been established that the activation of astrocytes plays a protective role during neurodegenerative processes resulting from inflammatory processes in the hippocampus during ischemia, reducing the level of TNFα and increasing the level of PI3K, as we have shown." (PMID 37569591, 2023). "Pro-inflammatory cytokines, such as IL-1β, IL-6, and TNF-α, were significantly increased in the hippocampus after ischemia induction, and Tat-CHIP attenuated the increase in pro-inflammatory cytokine release, suggesting the anti-inflammatory potential of Tat-CHIP in ischemic damage." (PMID 36450819, 2022). "We next assessed modulation of plasma levels of miR-329-5p, identified by reverse target prediction analysis based on its potential to regulate inflammatory and immune mediators (e.g., TLR-4, IL-1 and TNF-related signaling pathways) involved in ischemia and PC." (PMID 35359933, 2022). "Proinflammatory cytokines such as TNF-α exacerbate cerebral damage, whereas anti-inflammatory cytokines may be neuroprotective, suggesting that inflammatory responses during ischemia and reperfusion are important processes in neural injury." (PMID 36076942, 2022). "We conclude that the lactate/NDRG2/TNFα signaling axis may provide an extended mechanistic clue and a valuable approach for modulating neuroinflammation during the early stages of ischemia." (PMID 36572898, 2022).
ischemia (continued). "In the purpurin-treated ischemic group, IL-1β, IL-6, and TNF-α levels were significantly lower than those in vehicle-treated ischemic group and were 203.2%, 178.2%, and 626.1% of those in the control group 6 h after ischemia, respectively." (PMID 35094304, 2022). "It has been postulated that prolonged overexpression of TNF-α after ischemia may contribute to poor cardiac outcomes by increasing TNF-α when the myocardium undergoes both temporary ischemia and reperfusion." (PMID 35813433, 2022). "As an acute phase protein (APP), SAA was significantly upregulated in acute and chronic inflammatory conditions (such as trauma, infection, and ischemia), which was in response to the elevator of the inflammatory cytokines IL-6 and tumor necrosis factor (TNF)-α during the acute-phase response." (PMID 36090853, 2022). "Furthermore, ischemia-induced renal inflammation, mediated by TNF-α and interferon γ (IFN-γ), significantly enhanced TLR2 and TLR4 expression in the Henle’s loop and collecting ducts." (PMID 35682852, 2022). "Besides, NRP1 expression was tightly regulated by growth factors, transcription factors, and injury, e.g., tumor necrosis factor-alpha, Prox-1, and ischemia." (PMID 36425469, 2022). "TNF-α is not expressed in normal cardiomyocytes, but after myocardial infarction, the anoxia and ischemia activate cardiomyocytes and myocardial mononuclear macrophages, which will in its turn generate TNF-α in large amounts in the infarction boundary zone in the myocardium." (PMID 34373695, 2021). "CNCbl significantly improved spatial memory impairments (P<0.05), also CNCbl therapy significantly increased both glutathione (P<0.01) and superoxide dismutase (P<0.05) and reduced malondialdehyde (P<0.01) and TNF-α (P<0.05) in comparison with the ischemia group." (PMID 33953854, 2021). "Moreover, the pro-inflammatory factors COX-2, IL-6, IL-1β, and TNF-α were rarely expressed in the sham group, while their expression was remarkably elevated after ischemia." (PMID 35082676, 2021). "In addition, we observed the significant reduction of pro-inflammatory cytokines such as IL-6, IL-1β, and TNF-α in hippocampal homogenates 6 h after ischemia." (PMID 33435613, 2021). "When ischemia occurs, the expression of mmu-miR-155 was significantly upregulated, and inhibiting mmu-miR-155 could reduce the secretion of TNF-α, IL6, IL1β, and IFN-γ induced by neuroinflammation." (PMID 34457020, 2021). "Moreover, treatment with 100 mg/Kg bacailin significantly reduces the levels of pro-inflammatory cytokines, including IL-1β, IL-6, and TNF-α in the hippocampus of ischemia mice." (PMID 32084011, 2020). "Additionally, it inhibited the expression of NF-κB p65, IL-1β, and TNF-α and reduced the conversion of microglia to the M1 phenotype after ischemia." (PMID 32922507, 2020). "In addition, previous study has demonstrated that miR-181c-5p (named miR-181c in other studies) can directly target the 3′-untranslated region of TNFα mRNA, suppressing its mRNA and protein expression in rat microglial cells after ischemia injury." (PMID 32774684, 2020). "In order to provide additional evidence of the effect of CSO on inflammation following ischemic stroke, we used immunofluorescence staining to detect the expression of the microglia marker Iba1 and pro-inflammatory factor TNF-α in the ischemia penumbra 24 h after reperfusion." (PMID 32917229, 2020). "Indeed, TNF-α’s appearance in the brain following the damage induced by ischemia is quick and has a first peak in the early hours [1–3 h] and a successive one after more than 24–36 h." (PMID 32899616, 2020). "TNF-α-induced impairment of cerebrovascular function that associates to CBF deficits and secondary ischemia during SAH are thought to stem from altered S1P signaling as TNF-α alters S1P degradation, which leaves more S1P available for pro-constrictive S1PR2 signaling in mural cells." (PMID 32117979, 2020).
ischemia (continued). "Those with the M1 polarized phenotype secrete pro-inflammatory cytokines, such as IL-6, IL-1β, and TNF-α, which may further aggravate neuroinflammation in the peri-infarct region after ischemia and reperfusion injury." (PMID 31640144, 2019). "In addition, TNF-α level was significantly increased (about 1.7-fold, p < 0.05 and 1.8-fold, p < 0.05 of the ND sham group, respectively) at 2 and 5 days post-ischemia." (PMID 31546722, 2019). "When ischemia occurs, NF-κB translocates into the nucleus, then the pro-inflammatory factor genes are activated and followed by the release of a large number of inflammatory factors, including IL 6 and TNF α, which would further exacerbating organ injury." (PMID 32116668, 2019). "Reperfusion injury after ischemia is characterized by a severe immune response, including elevated reactive oxygen species and an increase in pro-inflammatory cytokines, including IL-1β, IL-6 and TNF-α." (PMID 31513644, 2019). "Obestatin treatment could increase both SOD and GSH (P<0.05) and reduce MDA and TNF-α (P<0.05) versus the ischemia group." (PMID 31231488, 2019). "However, post-ischemia melatonin administration was also able to decrease significantly TNF-α levels in both right and left hippocampus, as compared to their respective controls." (PMID 30029514, 2018). "Increased levels of IL-1β and TNF-α after ischemia are correlated with infarct severity." (PMID 28592261, 2017). "TNF-α, with its accomplice IL-6, induces the thrombin or even microthrombus formation on intestinal mucosa, leading to microcirculation disorder, grievous ischemia, and anoxia." (PMID 29156761, 2017). "Therefore, intermittent hypoxia can activate mTOR signal pathway to worsen cerebral injury by aggravating anoxia, ischemia and the release of inflammatory factors such as TNF-α in the central nervous system after cerebral ischemia." (PMID 28177899, 2017). "Our results identify microglial TNF as beneficial and neuroprotective in the acute phase and as a modulator of neuroinflammation at later time points after experimental ischemia, which may contribute to regenerative recovery." (PMID 27384243, 2016). "Regarding inflammatory pathways, guanosine reduces microglia activation induced by focal ischemia, and restores inflammatory mediators levels, like tumor necrosis factor (TNF-α), interferon-gamma (INF-γ) and interleukins, IL-1 IL-6 and IL-10 both in the CSF and infarcted area." (PMID 27699087, 2016). "In severe ischemia TNF-α levels appear to be elevated in affected brain tissue after 24 h." (PMID 26901230, 2016). "Compared to the sham-operated group, both TNF-α and IL-1β were markedly higher after ischemic injury in the ischemia group (P<0.05); however, treatment with LXW7 suppressed the expression of TNF-α and IL-1β, by 29 and 39%, respectively, compared to the ischemia group (P<0.05)." (PMID 27533766, 2016). "As plasma levels of IL1-β and TNF-α as apoptotic factors and inflammatory mediators were significantly elevated in I/R group compared to the control group, however, they were significantly decreased in ischemia only group compared to I/R group." (PMID 28101298, 2016). "Moreover, the administration of a LXA4 analog was found to induce IL-10 secretion and to prevent the tissue damage, TNF-α secretion and lethality of mice subjected to intestinal ischemia/reperfusion." (PMID 25853847, 2015). "TNF-α concentrations were also much higher than those of the ischemia and sham groups." (PMID 25677043, 2015). "Moreover, it has been reported that TNF-α concentration is increased in the cerebrospinal fluid in the ischemia." (PMID 26665003, 2015). "Compared with the ischemia group, the IL-1β and IL-6 serum levels were significantly reduced in the ischemia + low-, medium- and high-dose NaHS groups; in the ischemia + medium- and high-dose NaHS groups the TNF-α level in the serum was significantly reduced." (PMID 25667680, 2015).
ischemia (continued). "TNF-α levels are elevated both in the infiltrating inflammatory cells and hepatocytes in chronic liver injuries, including viral or alcoholic liver diseases, hepatitis, ischemia, and biliary obstruction." (PMID 25935744, 2015). "To test whether the activated microglia could trigger inflammatory reaction, we measured TNF-α, IL-1 expression level in the ischemia damaged brain tissue by ELISA." (PMID 26844229, 2015). "Furthermore, we confirmed that expression of TNF-α infiltration in leukocytes and apoptosis was observed after ischemia." (PMID 26665003, 2015). "The aim of this study was to investigate whether etanercept modulates neutrophil accumulation, TNF-α induction and oxidative stress in an ischemia/reperfusion injured rat heart model." (PMID 25260027, 2014). "Additionally, the therapeutic reagents that diminish either TNF-α or IL-1β production have been found in other models of neurological diseases, including ischemia, traumatic brain injury and SCI." (PMID 25014398, 2014). "And previous studies have already proved that the injection of antagonists of TNF-α and IL-1β could relieve the ischemia injury." (PMID 24707308, 2014). "In cultured microglia, activation by several stimuli depends on NHE1 mediated H+ homeostasis and inhibition of NHE1 with HOE 642 also reduced the production of superoxide anions as well as proinflammatory cytokines IL-1β, IL-6, and TNF-α induced by LPS or in vitro ischemia." (PMID 24392123, 2014). "Cell-adhesion molecules, particularly ICAM-1, are induced during the early stages of ischemia by TNF-α, along with other proinflammatory cytokines; subsequently, leukocytes begin to firmly adhere to endothelial cells, from where they can infiltrate into the brain tissue." (PMID 23972823, 2013). "Meanwhile, TNF-α has been reported to upregulate aSMase activity and subsequently modulate NF-κB-dependent inflammatory signaling, but the ischemia-induced activation of SMase is not linked to aSMase." (PMID 24007266, 2013). "Among them, TNF-α, IL-β, IL-8 and leukotriene may increase ischemia and injury of the intestinal mucosa." (PMID 23408793, 2013). "Our study is to the best of our knowledge the first to show that prophylactic CR suppresses injury-induced microglial activation, active caspase-3 induction and neuronal cell death in the injured rat cortex, consistent with the inhibitory effect of fasting on ischemia-induced increases of TNF-α." (PMID 22615943, 2012). "Levels of TNF-α at I/R 100 min (i.e., 100 min after ischemia) and 150 min were increased by 1.4-fold (P<0.05) and 2.3-fold (P<0.01), respectively, as compared to I/R 0 min (i.e., time right before ischemia)." (PMID 23056624, 2012). "Our results may be supported by earlier in vivo studies which show that the peptide reduced the levels of TNF-α in bronchoalveolar lavage fluid from rats with LPS-induced acute lung injury and in a model of intestinal ischemia/reperfusion-induced lung injury." (PMID 22685374, 2012). "In addition, ADAM-17 enhances shedding of tumor necrosis factor (TNF) after ischemia and an ADAM-17 antagonist reduces infarct size after transient middle cerebral artery occlusion." (PMID 22420304, 2012). "Previous studies have shown enhancement of neuronal damage by TNF-α in vivo in ischemia models." (PMID 22950459, 2012). "In light of this, modulating TNF expression in the retina may be an interesting alternative for the treatment of retinal injury following ischemia." (PMID 21152396, 2010). "Furthermore, an early increase in TNF-α mRNA has also been seen in a rat model of pressure-induced ischemia-reperfusion." (PMID 21152396, 2010). "Cellular signaling pathways involving TNF may be important in the development of retinal injury following ischemia and thus an interesting target for future development of pharmacological therapeutics." (PMID 21152396, 2010).
ischemia (continued). "Both endotoxin and TNF-α can directly induce local ischemia and increased permeability of intestinal mucosa, mediate the massive production of cytokines and pro-inflammatory response, and thereby induce the necrosis and apoptosis of cells as well as multiple organ dysfunction." (PMID 20169004, 2009). "Recent studies suggest that TNFα may affect brain endothelial cell function or microvascular integrity, even if its influence on regulation of cerebral hemodynamic function after ischemia remains ambivalent." (PMID 18947406, 2008). "In addition, smoking induces coronary vasoconstriction, stimulates the renin-angiotensin system, and increases inflammatory cytokines (e.g., interleukin-6 (IL-6), tumor necrosis factor-alpha (TNF-α)), contributing to plaque development, instability, and ischemia." (PMID 41306139, 2025). "Besides, TNF-α activates neutrophils and promotes adhesion and interaction between leukocytes and endothelial cells, increasing the infiltration of granulocytes into the ischemia–reperfusion area, resulting in myocardial damage." (PMID 38589925, 2024). "Interestingly, we observed that Tat-NTS peptide modulated ischemic brain injury-induced microglial polarization towards the anti-inflammatory phenotype and robustly decreased the expression of pro-inflammatory mediators IL-1β and TNF-α in ischemia-stimulated microglia." (PMID 37908731, 2023). "TNF α has a negative inotropic effect and is directly associated with the extent of myocardial damage after ischemia, which could also be an explanation for the inverse correlation with LV systolic function found in our study." (PMID 35683362, 2022). "However, the concentration of three cytokines, KC/GRO (CXCL1), IL-6, and TNFα, were showed to be significantly increased in the coronary effluents of the hearts after IR injury (after ischemia and 60 min of reperfusion) compared with the basal conditions (collected at 10 min stabilization, basal)." (PMID 34616778, 2021). "Therefore, miR-124 could negatively regulate PARP1 to alleviate renal ischemia-reperfusion injury by inhibiting TNFα/RIP1/RIP3 pathway, miR-124 may be exploited as a novel therapeutic agent to attenuate IRI in renal acute injury and kidney transplantation." (PMID 34131409, 2021). "TNF-α and IL-1β, as the pro-inflammatory cytokines released under different stimulation of many cell types, play a critical role in glia activation and infiltration of inflammatory cells, further aggravating brain edema and enlarging the damage to ischemia nerve cell injury after CIRI." (PMID 33927611, 2021). "As a proof of concept, we investigated whether MLR-HFS starting in the acute phase of ischemia and continued for 24 h was associated with an attenuation of proinflammatory mediators, namely IFN-γ, TNF-α, and IL-1α in the cerebral tissue surrounding the photothrombotic lesion." (PMID 33514001, 2021). "In addition, Tat-PGAM1, but not Control-PGAM1, significantly decreased microglial activation and secretion of pro-inflammatory cytokines, such as interleukin (IL)-1β, IL-6, and tumor necrosis factor (TNF)-α induced by ischemia in the ventral horn of the spinal cord." (PMID 33050051, 2020). "The increased expression of TNF-α after ischemia may up-regulate adhesion molecules such as ICAM-1, which can damage the endothelium and BBB, Overexpression of TNF-α exacerbates ischemic cerebral damage, whereas their inhibition decreases cerebral edema and infarct volume." (PMID 28486941, 2017). "During ischemia, inflammatory cells like macrophages may migrate into the ischemic myocardium and produce proinflammatory cytokines and chemokines, including TNFα, interleukin 6 (IL6), IL-1β, and monocyte chemotactic protein 1 (MCP-1), which further exacerbate myocardial I/R injury." (PMID 27190998, 2016). "Therefore, after induction of acute ischemia, we determined whether etanercept suppresses microglial activity and thus lowers the TNF-α level, helping to preserve the axons of the optic nerve." (PMID 27259948, 2016).